S100A10 (S100 calcium binding protein A10)
Diseases named in the same sentence as S100A10 in open-access papers (continued):
Sharing a sentence is not in itself a finding about the gene and the disease.
gastric cancer (continued). "Consistent with their findings with SAGE, S100A10 expression was significantly higher in 35% of the gastric carcinoma samples compared to normal gastric epithelia." (PMID 34944416, 2021). "Their results demonstrated that S100A10 was observed in low levels in normal gastric epithelia and was upregulated in gastric carcinoma tissues." (PMID 34944416, 2021). "From these results, K47succ-S100A10 appears to be highly specific in gastric carcinoma, which highlights the potential to be an excellent biomarker." (PMID 34944416, 2021). "Our previous results showed that succinylation was more a consistent protein modification than crotonylation and acetylation in GC and adjacent tissues, and succinylation of S100A10 by CPT1A promoted human gastric cancer (GC) invasion." (PMID 32859246, 2020). "Among them, four genes, including S100A2, S100A4, S100A7 and S100A10, were reported to overexpressed in gastric cancer previously." (PMID 18793447, 2008). "Furthermore, CPT1A causes the succinylation of S100A10 at K47, which inhibits ubiquitination and subsequent proteasomal degradation of S100A10, thereby promoting the invasion and migration of gastric cancer." (PMID 39781339, 2025). "For example, S100A10 was found to be succinylated at lysine 47 in gastric cancer." (PMID 35278714, 2023). "Thus, the results from this paper strengthen the evidence for the role of S100A10 in gastric cancer." (PMID 34944416, 2021). "From these results, S100A10 is upregulated in gastric cancer, including metastatic stages." (PMID 34944416, 2021). "As a whole, the results of this study indicate that S100A10 could be targeted to interfere with enzymes fueling tumor growth, making it a key protein in the identification and treatment of gastric cancer." (PMID 34944416, 2021). "S100A10 promoted malignant proliferation and suppressed cell apoptosis in gastric cancer." (PMID 33324631, 2020). "In addition, molecular analysis has revealed that several S100s, including S100A2, S100A4, S100A7 and S100A10, exhibit altered expression levels in gastric cancer." (PMID 18793447, 2008). "Both S100A2 and S100A10 genes were shown to be upregulated in gastric cancer of all three datasets." (PMID 18793447, 2008). "In gastric cancer, S100A10 and AHNAK2 are common DEGs that might be involved in Salmonella infection; however, annexin A2 is not, suggesting that the pathway might be actin independent or another protein is recruited to actin assembly sites at cellular membranes." (PMID 39228892, 2024). "CPT1A can promote the proliferation of breast cancer cells by succinylation of enolase 1 and enhance metastasis of gastric cancer (GC) cells by succinylation of S100A10." (PMID 33681201, 2021). "Thus, compared to other papers whose definition of increased expression is lower at 2- or 3-fold differences, this paper may be underrepresenting S100A10 upregulation in gastric carcinoma." (PMID 34944416, 2021). "Calcium binding protein S100A10 is reported to be overexpressed in renal cell carcinoma and may exert its effect on metastasis formation by stimulating the motility and invasive properties of gastric cancer cells." (PMID 12402156, 2002). "S100A10 is site specific succinylated at lysine 47 by CPT1A, which results in high levels of protein expression in gastric cancer." (PMID 40865948, 2025). "The succinic acidification mimic mutant S100A10(K47E) has also been used to further verify that CPT1A-mediated S100A10 succinylation increases the invasion and migration of gastric cancer cells." (PMID 36359005, 2022). "S100A10 accumulation, which is regulated by the succinyltransferase CPT1A and SIRT5-mediated desuccinylation, promotes gastric cancer cell invasion and migration." (PMID 31739800, 2019). "(2017) demonstrated that, although S100A10 expression did not correlate with long‐term survival in gastric cancer patients, it did, however, correlate with lymph node positivity which is consistent with our multimodel fitting of OS and RFS." (PMID 30009399, 2018).
gastric cancer (continued). "Among them, S100A4 and S100A6 have been reported to be epigenetically up-regulated in nasopharyngeal and gastric cancer by DNA hypomethylation over their gene promoter regions, while S100A2 and S100A10 down-regulated in head/neck and pituitary cancer by DNA hypermethylation." (PMID 28498804, 2017). "Additionally, it is demonstrated that S100A10 promotes the malignant growth of cancer cells by activating the AKT/mTOR signaling pathway in osteosarcoma and the Src/ANXA2/AKT/mTOR signaling pathway in gastric cancer." (PMID 36612197, 2022). "In addition, another study demonstrated that S100A10, a member of the calcium-binding cytoplasmic protein family, can bind to CPT1A at K47 and then be succinylated by it; contributing to the proliferation of gastric cancer cells." (PMID 36359005, 2022). "However, to our knowledge, no other reports related to galectin 3, S100A10, desmoplakin, occludin, keratins 8, 14, myosin VI, tubulin beta 4 and calveolin-3 in gastric cancer have been published." (PMID 12402156, 2002).
depression (29 papers, 2006 to 2025). "S100A10 has been implicated in the pathophysiology of depression and is being examined as a critical modulator of neurological functions." (PMID 37892132, 2023). "Reduced S100A10 expression in multiple brain regions in depressed individuals implicated S100A10′s role in depression pathology." (PMID 37892132, 2023). "Alterations of S100A10 (p11) level are also implicated in the etiology of major depressive disorder." (PMID 30760886, 2020). "In addition, its relative protein, s100a10 (p11), is widely implicated in depression-like behaviours in a region-specific manner." (PMID 38350966, 2024). "S100A10 has been widely described to play a key role in the brain in the context of depression, seizure, and neurodegenerative diseases." (PMID 40841353, 2025). "The expression of S100A10 in the brain has been extensively examined for its role in modulating mood-related behaviors, including major depressive disorder, Parkinson’s disease, and other neuropsychiatric disorders." (PMID 37892132, 2023). "The role of S100A10 in depression and as a regulator of the antidepressant response has been examined in various mouse and human studies." (PMID 37892132, 2023). "The S100A10-knock-out mouse models have been instrumental in studying the function of S100A10 in depression, mood disorders, and anxiety." (PMID 37892132, 2023). "S100A10 mediates its function in depression via interaction with the serotonin 1B receptor [5-hydroxytrptamin (5HT1B) receptor]." (PMID 37892132, 2023). "The most noteworthy of these studies is the role of S100A10 as a prognostic biomarker in cancer and depression." (PMID 37892132, 2023). "S100A10 (also called p11), a member of the S100 protein family, levels are reduced in postmortem brains of patients with depression." (PMID 36046712, 2022). "A striking pattern emerges from the molecular data to support the role of S100a10 neurons in the psychomotor and somatosensory aspects of a mouse endophenotype of depression." (PMID 31431686, 2020). "It is possible that the distribution of S100A10 in the brain is correlated with specific behavioral symptoms of depression." (PMID 31949486, 2020). "Taken together, both distribution and the number of cells expressing S100A10 in the brain play a mediatory role in depression disorder." (PMID 31949486, 2020). "Protein S100-A10 is mainly expressed in regions of the brain that are involved in the pathophysiology of depression, such as the nucleus accumbens, cerebral cortex and hippocampus." (PMID 24441568, 2014). "Additionally, we evaluated the role of the SNP sites of HTR1A, HTR1B, S100A10, BDNF genes in depression patients through genetic association analysis." (PMID 39130405, 2024). "S100A10 (p11) is an emerging player in the neurobiology of depression and antidepressant actions." (PMID 36046712, 2022). "Furthermore, synthetic glucocorticoid like dexamethasone can enhance the upregulation of p11, known as S100A10-protein, which is normally reported to down-regulated in patients with depression, a common comorbid symptom in PTSD." (PMID 32932645, 2020). "S100a10 expression is downregulated during depressive disorders, is essential for the antidepressant response, and shows enriched expression in specific cell types in brain regions relevant for depression." (PMID 32439846, 2020). "Interestingly, patients who had suffered from unipolar major depression disorder were found to have lower levels of both protein S100-A10 mRNA and protein, similar observations made in a mouse model of depression (H/Rouen mice)." (PMID 24441568, 2014). "Interfering with these S100A10 interactions could be envisioned for the treatment of the corresponding diseases, including depression, although a beneficial effect of an upregulation of S100A10 expression, e.g., through 1,25-dihydroxyvitamin D3, still needs to be demonstrated." (PMID 29914106, 2018).
depression (continued). "Therefore, protein S100-A10 may play an important role in depression, through its ability to modulate 5-HTR expression at the cell-surface." (PMID 24441568, 2014). "The S100a10 gene and its associated protein p11 are important in the regulation of serotonin receptors, and decreases in S100a10 gene expression have been linked to PTSD, major depressive disorder, and bipolar disorder and proposed as a likely biomarker for suicidality." (PMID 25165739, 2014). "The adaptor protein p11 (also known as S100A10) plays a role in G-protein coupled receptor (GPCR) signaling, with implications in animal models of major depressive disorder and anxiety." (PMID 39934408, 2025). "Therefore, it was hypothesized that protein S100-A10 may play a role in depression." (PMID 24441568, 2014). "However, the mechanisms through which S100A10 interacts with the 5-HT1B receptor and their attributions to depression remain a mystery, which requires further investigations." (PMID 31949486, 2020). "Experiments designed to consider a more general role of S100 proteins in depression and antidepressant mechanisms as opposed to focusing solely on S100A10 might generate important new findings." (PMID 16722532, 2006). "In non-tumor diseases, the distribution of S100A10 in the brain and its interaction with 5-hydroxytryptamine 1B (5-HT1B) receptor, an important mediator in the central nervous system that maintains a dynamic balance of the neurotransmitters, correlates with depression-like behavior." (PMID 31949486, 2020). "In the absence of S100A10, the metabolites of 5-HT are expectedly elevated, which may be induced by the decreased localization of 5-HT1B receptor at the cell surface, and several depression-like phenotypes also display increased thigmotaxis and immobility as well as decreased horizontal activities." (PMID 31949486, 2020).
colorectal cancer (25 papers, 2007 to 2024). A primary or metastatic malignant neoplasm that affects the colon or rectum. "The S100A10 gene was implicated in many malignancies, including thyroid carcinoma, colorectal cancer, and ovarian cancer." (PMID 37133437, 2023). "We have shown that loss of S100A10 protein results in the inhibition of invasiveness in HT‐1080 fibrosarcoma and Colo222 colorectal cancer cells and decrease in in vivo tumor growth of Lewis lung carcinoma (LLC) cells." (PMID 30009399, 2018). "Increased S100A10 expression is independently associated with recurrence in colorectal cancer patients." (PMID 30572596, 2018). "In colorectal cancer cells, S100A10 expression are associated with resistance to oxaliplatin (L-OHP)." (PMID 30558666, 2018). "RNA interference-mediated downregulation of S100A10 gene expression in colorectal cancer cells, has been shown to result in a complete loss in plasminogen-dependent cellular invasiveness." (PMID 18827820, 2008). "The finding that S100A10 was hypermethylated in medulloblastoma cell lines and tumours was unexpected, as its overexpression has previously been associated with plasminogen-dependent cellular invasiveness in fibrosarcoma and colorectal cancer cells." (PMID 17579622, 2007). "Cancer types in which the expression of both GRHL2 and S100A10 is simultaneously increased include hepatocellular carcinoma, non-small-cell lung cancer, colorectal cancer, and pancreatic ductal adenocarcinoma." (PMID 34356598, 2021). "S100A10 is an oncogenic event in various malignancies, including thyroid anaplastic carcinoma, colorectal cancer and ovarian cancer." (PMID 33815482, 2021). "Several studies in the past decade have highlighted the importance of S100A10 as s potential biomarker in colorectal cancer." (PMID 34944416, 2021). "Several studies have proved that the expression of S100A10 was closely related to the sensitivity of colorectal cancer to chemotherapy drug oxaliplatin (L-OHP)." (PMID 31949486, 2020). "COLO-320 colorectal cancer cells that overexpress S100A10 also show reduced sensitivity to oxaplatin." (PMID 30572596, 2018). "(2013) revealed a correlation between positive S100A10 protein expression and poor tumor differentiation, disease stage, and poor OS in colorectal cancer patients." (PMID 30009399, 2018). "S100A10 was overexpressed in renal cell carcinoma, anaplastic thyroid carcinoma, gallbladder, and colorectal cancer." (PMID 29607329, 2018). "Knockdown of S100A10 by siRNA significantly reduces the migration capacity of two colorectal cancer cell lines, HCT-116 and DLD-1." (PMID 30572596, 2018). "Decreased expression of S100A10 in HT1080 fibrosarcoma cells and colorectal cancer cells weakened their invasiveness and metastatic potential, suggesting that S100A10 contributes to cancer cell invasiveness." (PMID 29607329, 2018). "Likewise, the knockdown of S100A10 significantly reduced the proliferation and metastasis capacity of colorectal cancer cells." (PMID 36612197, 2022). "This also reflects the promotion of S100A10 to the progression of colorectal cancer from the side." (PMID 31949486, 2020). "The role of S100A10 in oxaliplatin sensitivity in human colorectal cancer has also been noted." (PMID 31739800, 2019). "Additionally, S100A10 has been proposed as a prognostic marker for colorectal cancer as S100A10 overexpression is correlated with poor differentiation and increased mortality in colon cancer patients." (PMID 29324674, 2018). "Knockdown of S100A10 by siRNA significantly reduces the invasion capacity of HCT-116 and DLD-1 colorectal cancer cell lines." (PMID 30572596, 2018). "In addition, we have previously demonstrated that S100A10 colocalizes with uPA receptor (uPAR) at the cell surface of HT1080 fibrosarcoma and Colo222 colorectal cancer cells to drive plasminogen activation." (PMID 30009399, 2018).
colorectal cancer (continued). "Our recent proteomics studies have demonstrated that intracellular protein expression levels of S100A10 are significantly correlated with the sensitivity of colorectal cancer (CRC) cells to L-OHP, but not 5-FU, suggesting that S100A10 is a candidate predictive marker for the response to L-OHP." (PMID 24851084, 2014). "S100A10 alone in the absence of annexin A2 is crucial for promoting plasmin production and the invasiveness of CCL-22 colorectal cancer cells." (PMID 30572596, 2018).
ovarian carcinoma (18 papers, 2018 to 2023). A malignant neoplasm originating from the surface ovarian epithelium. "Several other studies have also published similar observations in ovarian cancer, where increased S100A10 expression is associated with poor response to chemotherapy and overall survival." (PMID 37892132, 2023). "The present results clearly show that the upregulated expression of S100A10 in ovarian cancer is associated with carboplatin resistance, age at diagnosis and tumor grade." (PMID 31739800, 2019). "Our previous studies reported that annexin A2 plays an important role in ovarian cancer invasion and metastasis and increased expression of both annexin A2 and S100A10 is associated with poor serous ovarian cancer outcome." (PMID 30621740, 2019). "We recently demonstrated that high stromal annexin A2 and high cytoplasmic S100A10 expression is associated with a 3.4-fold increased risk of progression and 7.9-fold risk of death in ovarian cancer patients." (PMID 30572596, 2018). "Interestingly, stromal ANXA2 staining and cytoplasmic S100A10 immunostaining correlated with increased risk of ovarian cancer progression and death." (PMID 34944416, 2021). "Moreover, it was shown that ovarian cancer patients with high expression of cytoplasmic S100A10 and stromal Annexin A2 have a 3.4-fold increased risk of progression and a 7.9-fold higher risk of cancer-related death." (PMID 32722137, 2020). "Moreover, high stromal annexin A2 and high cytoplasmic S100A10 expression in serous ovarian cancer tissues are associated with a 3.4-fold increased risk of progression and a 7.9-fold risk of ovarian cancer death." (PMID 30572596, 2018). "It is reported that decreased S100A10 expression not only inhibits ovarian cancer cell proliferation and colony formation in vitro but also remarkably suppresses ovary tumor growth in vivo." (PMID 36612197, 2022). "Recently, Cui’s group reported that S100A10 was an oncogene in ovarian cancer by promoting tumor metastasis, and reduced sensitivity to carboplatin." (PMID 34178044, 2021). "A more recent study evaluated the immunostaining of both ANXA2 and S100A10 in a large cohort of epithelial ovarian cancer tissue samples and found that enhanced expression of both proteins in the stroma was associated with reduced OS." (PMID 34944416, 2021). "Nevertheless, among others, S100A3, S100A10, and S100B were identified to be related to drug resistance in ovarian cancer." (PMID 32722137, 2020). "Together, the results of the present study reveal that S100A10 expression can be used as a predictive marker for the prognosis of ovarian cancer and chemosensitivity to carboplatin." (PMID 31739800, 2019). "In carboplatin-sensitive ovarian cancer tissues, weak cytoplasmic expression of S100A10 was observed." (PMID 31739800, 2019). "The aims of the present study were to investigate the functional role of S100A10 in the progression and carboplatin sensitivity of ovarian cancer." (PMID 31739800, 2019). "In the present study, the knockdown of S100A10 was found to inhibit the migration and invasion in human ovarian cancer cells." (PMID 31739800, 2019). "We also found that the expression of S100A10 was detected in the cytoplasmic compartment of carboplatin-resistant ovarian cancer tissues." (PMID 31739800, 2019). "In carboplatin-resistant ovarian cancer tissues, strong cytoplasmic expression of S100A10 was observed." (PMID 31739800, 2019). "In this study, we initially analyzed the association between S100A10 expression and clinical outcomes of ovarian cancer patients to evaluate the feasibility of S100A10 as a prognostic biomarker." (PMID 31739800, 2019). "While the effects of ATRA on ovarian cancer cell proliferation and apoptosis have been previously investigated, to date no data has been reported on the effects of ATRA on both annexin A2 and S100A10 expression in ovarian cancer cells." (PMID 30572596, 2018).